MUC16 (mucin 16, cell surface associated)
Diseases named in the same sentence as MUC16 in open-access papers (continued):
Sharing a sentence is not in itself a finding about the gene and the disease.
breast carcinoma (continued). "Additionally, the CDK4/6 inhibitor palbociclib, by downregulating MUC16 expression, exerts an inhibitory effect on the expression of key genes in the breast cancer cell cycle and suppresses ER(-) aggressive breast cancer cells." (PMID 38361923, 2024). "Besides MUC16, other members of the mucin family, including MUC19 and MUC1 have been implicated in the glucose metabolism of different cancers, including breast cancer, bladder cancer, and endometrial carcinoma." (PMID 39219440, 2024). "Furthermore, decreased MUC16 expression results in an accumulation of breast cancer cells at the G2/M phase of the cell cycle via Cyclin B1 and phosphorylation of AURKA, which in turn leads to apoptosis of breast cancer cells through JNK signaling." (PMID 39149564, 2024). "Our previous reports indicated that MUC16 could induce the G2-M transition of breast cancer cells by interacting with Janus kinase 2 (JAK2), which in turn enhances the phosphorylation of STAT3 (Y705) and Aurora Kinase A." (PMID 36918912, 2023). "Interestingly, previous findings suggest a role for MUC16 in promoting metastasis, therapy resistance, and disease progression in multiple malignancies, including breast cancer." (PMID 37761830, 2023). "MUC16 is significantly elevated in breast cancer patients who after chemotherapy." (PMID 36918912, 2023). "However, it is notable that, in fact, ER-negative HER2-positive breast cancer patients with high gene expression of CAIX or MUC16 trended towards better recurrence-free survival intervals than those with low gene expression." (PMID 35267611, 2022). "In addition to this, it has been reported that increased quantities of soluble MUC16 were found in a variety of cancers, including breast cancer, mesothelioma, gastric cancer, colorectal adenocarcinoma, and some others." (PMID 36051359, 2022). "Recent studies also discovered frequent non-silent MUC16 mutations in breast cancer, another cancer type in which MUC16 was observed to be overexpressed." (PMID 33946379, 2021). "Finally, in experimental animal tumor models, 14D11 treatment led to prolongation of overall survival in animals bearing flank tumors, and retarded lung specific metastatic growth by MUC16 expressing breast cancer cells." (PMID 33580170, 2021). "In addition, four cytokeratin genes (KRT8, KRT16, KRT17, and KRT19) and eight tumor-associated genes (TERT, MUC16/M17S2/CA125, CD44, TWIST1, TACSTD1/EpCAM/CD326/ESA/HEA125/GA733, DPP4/CD26, ESR1, and PGR), were upregulated in CRC and breast cancer samples." (PMID 29882767, 2018). "MUC16 is used as tumor marker for some human cancers including breast cancer." (PMID 29202842, 2017). "Furthermore, we checked the protein level of MUC16, β-catenin and three Wnt downstream genes, Snail, Axin2 and Cyclin D1 in three sets of human breast cancer samples by Western blot." (PMID 27167110, 2016). "Previously MUC16 was shown to induce rapid G2/M transition in MDA-MB-231 breast cancer cells." (PMID 25691062, 2015). "In addition, ectopic expression of different lengths of carboxyl-terminal MUC16 (283 and 413 amino acids) in ovarian, colon and breast cancer cells resulted in increased metastatic and chemo resistant properties, suggesting it to be critical in mediating the functions of MUC16." (PMID 25691062, 2015). "Mechanistically, we demonstrated that MUC16-Cter results in nuclear translocation of JAK2, which preferentially phosphorylates histone-3 and up regulates stemness-specific genes such as LMO2 and NANOG, which was further validated using Jak2 deficient (Jak2−/−) mouse mammary tumor cells." (PMID 25691062, 2015).
breast carcinoma (continued). "Predictions of known cancer driver genes in new cancer types include SPTA1, CHD4 and ASXL1 in colorectal cancer, FOXO3, MUC16 and ZFPM1 in breast cancers and CNTNAP2, CTNND2 and TRRAP in lung adenocarcinoma." (PMID 38890488, 2024). "The clinical significance of MUC16 and ELAVL1 or Hu antigen R (HuR) was examined using breast cancer TCGA data." (PMID 36918912, 2023). "Our novel mutations in NCOR1, MUC4, and MUC16 genes should be validated in further mechanistic studies and translational studies so that those mutations might serve as predictive biomarkers or therapeutic targets for patients with CDK4/6 inhibitor-resistant breast cancer." (PMID 33504001, 2021). "Additional findings that are noteworthy are that we identified the 39 most frequently mutated genes in CTCs and metastases, and some of them such as MUC16, ANKRD36, and DNAH5 are known to be biologically important in breast cancer." (PMID 32650480, 2020). "A more pronounced effect of MUC16-Cter is observed in LMO2 expression compared to NANOG in T3M4 and Jak2+/+ mammary tumor cells." (PMID 25691062, 2015). "MUC16 (CA125) is a well characterized biomarker in several human malignancies including ovarian, pancreatic and breast cancer." (PMID 24447304, 2014). "More importantly, there was a significant upregulation of MUC16 expression in the non-responder breast cancer patients compared to the chemotherapy responders, with an AUC (sensitivity and specificity) of 0.573 (P = 2.6e−03)." (PMID 36918912, 2023). "Moreover, the expression differences of MUCs among various major stage in breast cancer were also assessed using GEPIA database, and the results showed that only MUC16 and MUC14 presented statistical significance." (PMID 34828282, 2021). "Disruption of MSLN/MUC16 interaction by MesobsFab cannot explain this result because MUC16 expression has not been documented in breast cancer." (PMID 31354732, 2019). "Adjusting for family history of ovarian or early onset breast cancer and personal history of breast cancer did not change estimates for any of the MUC1 or MUC16 polymorphisms." (PMID 24551091, 2014). "Another study found that the overexpression of MUC16 induces breast cancer cell proliferation via its interaction with the non-receptor tyrosine kinase JAK2, and this interaction mediates phosphorylation of transcription factor STAT3, which may transactivate c-Jun for Cyclin D1 expression." (PMID 39149564, 2024). "FAT3, MUC16, and SYNE1 have also been mentioned as common mutant genes in breast cancer in previous studies, but there is no specific report on whether they affect the development and prognosis of breast cancer." (PMID 33968045, 2021).
lung cancer (56 papers, 2014 to 2026). A malignant neoplasm involving the lung. "MUC16 was overexpressed in both human primary lung carcinoma and associated lymph node metastases, potentially playing a role in the epithelial-to-mesenchymal transition during lung cancer cell metastasis." (PMID 40718829, 2025). "As well, increased expression of mutated MUC16 promotes the proliferation and growth of lung cancer." (PMID 36552994, 2022). "Mutations in anti-matrix metalloproteinase mucin 16 (MUC16) have been reported to be potentially associated with air pollution, thus contributing to the development of air pollution-associated lung cancer." (PMID 36685819, 2022). "As a result, they believe that MUC16 overexpression caused by gene alterations has functional implications for lung cancer cell behaviors." (PMID 36552994, 2022). "In a large investigation of lung cancer, MUC16 gene mutations were found in 53 percent of cases, including 51 percent of adenocarcinoma and 56 percent of squamous cell carcinoma." (PMID 36552994, 2022). "This matched the findings of Kim and colleagues, who found MUC16 to be highly mutated in many malignant tumors, such as lung cancer." (PMID 36552994, 2022). "MUC16 overexpression induced by gene mutations promotes lung cancer cell growth, metastasis and chemoresistance." (PMID 36685819, 2022). "The high MUC16 expression caused by gene mutations affected cell proliferation, migration, and invasion in cultured lung cancer cells in this work." (PMID 36552994, 2022). "For example, mutations in MUC16 gene are observed in 50% of lung cancer patients residing in Xuanwei and dysregulation of MUC16 was involved in the progression of Xuanwei lung cancer." (PMID 33796457, 2021). "It was shown that in lung cancer, MUC16 mutations can lead to its oncogenic upregulation and the overexpression of MUC16 is associated with increased tumour cell growth, cancer cell migration, and resistance to cytotoxic drugs." (PMID 33946379, 2021). "MUC16 mutations are associated with MUC16 mRNA and protein up-regulation, furthermore promotes the proliferation, enhances migration and invasion and increases cisplatin resistance of lung cancer." (PMID 32807223, 2020). "MUC16 has also been implicated in the development of other neoplasms and as a potential marker in pancreatic, breast and lung cancers." (PMID 33680922, 2020). "Among the genes involved in cell adhesion, MUC16, associated with hypermutation and favorable prognosis in GC, and with resistance to chemotherapy in lung cancer, was the top discriminator of the INT and COD subtypes." (PMID 31773340, 2020). "We then investigated the impacts of MUC16 gene mutation on MUC16 expression and cell behavior in cultured lung cancer cells by inducing certain mutations within this gene using CRISPR/Cas9 genome editing technology." (PMID 29552305, 2018). "Analogously, a recent study has also reported a strong association between increased MUC16 expression and aggressiveness of cisplatin resistant lung cancer cells." (PMID 29552305, 2018). "Our previous study demonstrated that 50% of air pollution-related lung cancers contain a mutated MUC16 gene." (PMID 29552305, 2018). "Therapeutic inhibition of MUC16 may restore apoptotic susceptibility and suppress metastatic spread in lung cancer." (PMID 42038028, 2026). "As well, increased expression of mutated MUC16 enhances lung cancer cells proliferation and growth." (PMID 36552994, 2022). "MUC16 has been linked to the development and spread of numerous malignancies, although its role in lung carcinoma is unknown." (PMID 36552994, 2022).
lung cancer (continued). "This cohort study examines whether MUC16 mutation is associated with response to treatment with immune checkpoint inhibitors and outcomes among patients with solid tumors, non–small cell lung cancer, and melanoma." (PMID 32845327, 2020). "Additionally, MUC16 overexpression induced by gene mutations had functional effects on the behavior of lung cancer cells, including increasing their resistance to cisplatin, promoting their growth, and enhancing their migration and invasion capabilities." (PMID 29552305, 2018). "Thus, we suggest that MUC16 overexpression induced by gene mutations have functional impacts on cell behaviors, such as proliferation, migration, and invasion, in lung cancer." (PMID 29552305, 2018). "Based on previous studies and our present study, we speculate that MUC16 gene overexpression induced by gene mutations is not only a phenomenon, but also plays a functional role in the development and progression of lung cancer." (PMID 29552305, 2018). "Based on the data, we suggest that MUC16 mutations potentially associated with air pollution may participate in the development and progression of air pollution-related lung cancer." (PMID 29552305, 2018). "Our results demonstrated that MUC16 up-regulation and gene mutation occurred simultaneously in air pollution-related lung cancer, and MUC16 up-regulation and mutation were associated with the degree of air pollution or, more precisely, the degree of PAH exposure." (PMID 29552305, 2018). "In total, 22 tissue samples (10 pairs of NSCLC and their adjacent nonmalignant tissues as well as two cancerous tissues) and 10 lung cancer cell lines were selected for sequencing of the captured target gene to analyze the distribution of mutations within the MUC16 gene." (PMID 29552305, 2018). "Based on these data, we hypothesized that air pollution and PAH exposure may cause MUC16 gene mutations, which can subsequently lead to changes in MUC16 mRNA expression in air pollution-related lung cancer." (PMID 29552305, 2018). "Furthermore, sequencing of the captured MUC16 gene identified 561 mutation sites within the MUC16 gene in the air pollution-related lung cancer tissues." (PMID 29552305, 2018). "Finally, we investigated the effects of MUC16 overexpression induced by gene mutations on cell growth, migration, and invasion in cultured lung cancer cells." (PMID 29552305, 2018). "The MUC16 gene is one of the most frequently mutated genes in air pollution-related lung cancer." (PMID 29552305, 2018). "Taken together, these findings indicate that MUC16 overexpression induced by gene mutations may promote the invasion and metastasis of lung cancer." (PMID 29552305, 2018). "Moreover, in air pollution-related lung cancers, MUC16 mutations have been shown to be particularly prevalent, indicating that environmental factors may influence its expression and, subsequently, the tumor-associated immune responses." (PMID 40655139, 2025). "Thus, increased expression of mutated MUC16 promotes the proliferation and growth of lung cancer." (PMID 36552994, 2022). "Our study demonstrated that MUC16 up-regulation induced by gene mutations may be involved in the development and progression of lung cancer and that MUC16 may be a potential marker for diagnosis, predicting prognosis, monitoring recurrence, and guiding the treatment of NSCLC." (PMID 29552305, 2018). "Thus, MUC16 mutations potentially caused by air pollution may participate in the development and progression of air pollution-related lung cancer." (PMID 29552305, 2018). "Our previous study determined that mutations in the MUC16 gene were observed in 50% of lung cancer patients residing in Xuanwei and Fuyuan, and the MUC16 gene is among the top frequently mutated genes, thus providing a clue that MUC16 may be associated with air pollution-related lung cancer." (PMID 29552305, 2018).
lung cancer (continued). "MUC16, a transmembrane glycoprotein, is overexpressed in lung cancer, particularly in patients exposed to indoor air pollution." (PMID 40831928, 2025). "In the lung cancer tumor microenvironment, MUC16 suppresses innate immune responses through multiple mechanisms, thereby promoting tumor immune evasion." (PMID 40655139, 2025). "Endoplasmic reticulum oxidoreductase 1L (ERO1L), a key enzyme in disulfide bond formation, significantly affects MUC16 expression in lung cancer." (PMID 38758220, 2024). "In exosomes, it was seen that MUC16 was upregulated in primary lung cancer whereas it was downregulated in liver metastasis." (PMID 38877052, 2024). "Overexpression of MUC16 in lung cancer enhances tumor growth and migration, while also influencing development and metastasis through the JAK2/STAT3/GR axis, potentially contributing to chemotherapy resistance to agents like cisplatin and gemcitabine." (PMID 38361923, 2024). "Overexpression of MUC16 can promote the growth, migration, invasion, and cisplatin resistance of lung cancer cell." (PMID 38758220, 2024). "Further, we have shown that MUC16 promotes lung cancer migration via STAT3/glucocorticoid receptor (GR)/testis-specific protein Y-encoded-like 5 (TSPYL5) axis." (PMID 36918912, 2023). "The following carboxy-terminal fragment of MUC16 (referred to as MUC16-Cter) has been shown to confer tumorigenic, metastatic, and drug-resistant properties to the pancreatic and lung cancer cells." (PMID 37567918, 2023). "MUC16, PRX, and SDHA showed the highest frequency of deleterious mutations, occurring in all primary lung cancers and BMs (Case 2, Case 3, Case 5, and Case 7)." (PMID 37384291, 2023). "For analyzing mutation distribution in the MUC16 gene, 22 tissue samples (10 pairs of NSCLC and their neighboring nonmalignant tissues, in addition to two carcinogenic tissues) and 10 cell lines of lung cancer were chosen for captured target gene sequencing." (PMID 36552994, 2022). "MUC16 performs a meaningful function in metastasis and tumourigenesis in lung cancer by regulating TSPYL5 through JAK2/STAT3/GR." (PMID 36059804, 2022). "High MUC16 expression contributed to the capacity of lung cancer cells to proliferate, invade, resist chemotherapy, and migrate in experiments analyzing cell behaviour." (PMID 36059804, 2022). "Likely, MUC16-Cter overexpressing lung cancer cells (A549-F114HA) were more resistant to the cisplatin and gemcitabine cytotoxic effects." (PMID 36552994, 2022). "What is more, other mutated genes, such as TTN, MUC16, and RYR2, all previously reported to regulate tumorigenesis and chemoresistance in lung cancer, were the most common mutations in both cohorts, indicating a lack of significant immune infiltration." (PMID 36246963, 2022). "A MUC16 knockdown also markedly decreases lung cancer cell migration via JAK2/STAT3/GR (glucocorticoid receptor)-mediated TSPYL5 (testis-specific protein Y-encoded-like 5) downregulation." (PMID 34681277, 2021). "Previously, we reported that MUC16 is overexpressed in pancreatic, breast and lung cancer and promotes a rapid G2/M checkpoint transition through its interaction with JAK2/STAT3, leading to accelerated proliferation." (PMID 32709695, 2020). "In the present study, we first analyzed MUC16 mRNA expression in lung cancer tissues from patients residing in air-polluted regions (Xuanwei and Fuyuan)." (PMID 29552305, 2018). "In a general study of lung cancer, 53% (302/572) of lung cancers, including 51% (202/394) of AD and 56% (100/178) of SCC, showed mutations in the MUC16 gene." (PMID 29552305, 2018). "On the other hand, TTN and/or MUC16 were still retained in the top 10 for some cancers such as large intestine and lung cancers, suggesting their tumorigenic relevance to these cancers." (PMID 26212640, 2015). "The impact of MUC1 and MUC16 in lung cancer development has been further substantiated." (PMID 38361923, 2024).